CDK4 (cyclin dependent kinase 4)
Diseases named in the same sentence as CDK4 in open-access papers (continued):
Sharing a sentence is not in itself a finding about the gene and the disease.
breast cancer (continued). "As three CDK4/6 inhibitors have recently received FDA approval for life-long breast cancer therapy, our study provides a preclinical basis for their expedient repurposing for obesity management." (PMID 30185666, 2018). "We observed that transfection with SALL1 significantly increased the gene expressions of Cyclin A2, Cyclin B1, Cyclin E1, CDK2 and CDK4 in breast cancer MDA cells, which are important for checkpoint regulation in G1-S transition and S phases." (PMID 29625565, 2018). "In breast tissue, the CDK4/cyclin D1 axis appears critical for cancer initiation, as demonstrated using animal models and analysis of human breast cancer specimens." (PMID 29669860, 2018). "This trial (NCT01872260) involved a study of triple therapy with BYL719 (PI3K-⍺ inhibitor), LEE011 (CDK4/6 inhibitor), and letrozole in advanced ER+ breast cancer." (PMID 30382095, 2018). "Using the PI3K/PTEN/CDK4/6 pathways in breast cancer as an example, we demonstrate how analysis can be performed in tandem with trial enrollment and can evaluate downstream signaling following therapeutic inhibition." (PMID 30382095, 2018). "ER+ breast cancer depends on the cyclin D1-CDK4/6-RB pathway for growth and this pathway is targeted by CDK4/6 inhibitors." (PMID 29963233, 2018). "The only biomarker that is clinically used for CDK4/6 inhibitor treatments is hormone receptor positivity in breast cancer." (PMID 30293995, 2018). "CDK4 & 6 inhibitors have enhanced the effectiveness of endocrine therapy (ET) in patients with advanced breast cancer (ABC)." (PMID 30588487, 2018). "Clinical studies of breast cancer leading to FDA approval demonstrated that CDK4/6 inhibitors in combination with endocrine therapy exhibited superior activity compared with endocrine therapy alone." (PMID 30135856, 2018). "For example, Palbociclib can block the propagation of lung, ovarian and breast cancer stem cells by targeting on CDK4." (PMID 29723215, 2018). "The actions of CDK4/6, through the phosphorylation of Rb, are pivotal in the transition from G1 to S phase in ER+ breast cancer cells." (PMID 30301939, 2018). "Deletion of the CDK4/6 inhibitor p18INK4C stimulates luminal progenitor expansion and mammary tumor formation in mice." (PMID 29921600, 2018). "CDK4/6 inhibitors have emerged as potent agents in the treatment of metastatic ER+ breast cancer in combination with endocrine treatment." (PMID 30489256, 2018). "Small molecule inhibitors of CDK4/6 have been demonstrated clinically effective in combination with hormonal/endocrine therapy against several types of cancers, especially breast cancer." (PMID 30135856, 2018). "Further investigations are necessary to evaluate the potential role of Cdk4/6 and PI3K pathway inhibitor combinations for treating breast cancer, at the same time, we are reporting the first use of Cdk4/6 and PI3K inhibitors in NPC model." (PMID 29789630, 2018). "Given that the majority of breast cancer is initially positive for steroid hormone receptors, blockade of CDK4/6 activity by small molecule inhibitors represents a rational strategies and has proven efficacious in the treatment of breast cancer." (PMID 30135856, 2018). "Here, the authors investigate ctDNA in CDK4/6 inhibitor treatment in advanced breast cancer, finding ctDNA levels predict progression-free survival and anticipate clonal selection." (PMID 29497091, 2018). "Palbociclib (PD-0332991) is a selective CDK4/6 inhibitor approved for use in combination with letrozole to treat hormone receptor-positive advanced breast cancer as initial endocrine therapy." (PMID 30135856, 2018). "Other CDK4/6 inhibitor-based regimens have also demonstrated efficacy in elderly patients, further supporting CDK4/6 inhibitors as a valuable treatment option in elderly patients with HR+ advanced breast cancer." (PMID 29058175, 2018). "We selected a FDA approved cell cycle inhibitor “palbociclib” (PAL, CDK4/6 inhibitor) currently used in breast cancer." (PMID 30236142, 2018).
breast cancer (continued). "Many studies have since demonstrated the requirement of CDK4/6 in numerous solid tumors and hematologic malignancies, particularly breast cancer." (PMID 30443290, 2018). "Cyclin-dependent kinases 4 and 6 (CDK4/6) are core cell-cycle components, essential to initiation and development of breast cancer and T-ALL." (PMID 30191140, 2018). "CDK4/6 inhibitors (CDK4/6i) showed effectiveness against glioblastoma, breast cancer and melanoma by arresting tumor cell cycle at G1, via inhibition of retinoblastoma tumor suppressor phosphorylation." (PMID 30191140, 2018). "Estrogen receptor (ER)+/HER2- breast cancers have shown great progression free survival when CDK4/6 inhibitors are combined with endocrine therapies." (PMID 29963233, 2018). "Tumor cell arrest during the G1/S transition, by inhibitors of Cdk4/6, is one of the new avenues for breast carcinoma treatment." (PMID 29911682, 2018). "In vivo, G1T38 treatment led to equivalent or improved tumor efficacy compared to the first-in-class CDK4/6 inhibitor, palbociclib, in an ER+ breast cancer xenograft model." (PMID 28418845, 2017). "Two cases with PIK3CA mutated breast cancer had partial responses to a combination of PIK3CA inhibitor, CDK4/6 inhibitor and hormonal therapy." (PMID 28915716, 2017). "A novel amiRNA, miR p-27-5p, which targets the 3′-untranslated region (3′-UTR) of cyclin-dependent kinase 4 (CDK4) mRNA, was introduced into breast cancer cells." (PMID 28075356, 2017). "Cyclin D1 acts as an oncogene in breast cancer by giving selective advantages to cancer cells, such as activation of its partner CDK4 and other cell cycle regulators for deregulating normal pathways and leading to abnormal cell cycle progression." (PMID 28152041, 2017). "In HER2-driven or oncogenic HRAS-driven breast cancer in mice, tumor development was specifically protected by depleting cyclin D1 or CDK4 or expressing the CDK4- or CDK6-specific inhibitor INK4A or a dominant-negative mutant form of K112E cyclin D1." (PMID 28474232, 2017). "The majority of ER+ breast cancer cells, however, do have intact Rb and it is therefore urgent to identify other clinically useful predictive biomarkers before treatment with CDK4/6 inhibitors." (PMID 27923036, 2017). "The topic of CDK4/6 inhibitors in breast cancer was chosen because it was a timely, representative topic in the field of precision cancer medicine with an active knowledge gap." (PMID 28743680, 2017). "Targeting the cell cycle as anticancer therapy has been actively investigated for decades, and recently, tremendous progress has been made as the highly selective CDK4/6 inhibitor palbociclib received FDA approval for breast cancer treatment." (PMID 28453226, 2017). "Second, the associations of the proportions of tumors having the different predicted CDK4 modification profiles with key clinical features were confirmed in an independent cohort of 4,034 breast cancer patients with published gene expression profiles." (PMID 28566333, 2017). "We therefore measured changes in CDK2 and CDK4 expression in both HR-NB and breast cancer because CDK2 is a marker of ESCs, whereas CDK4 is a marker of adult stem cells." (PMID 28246384, 2017). "First, to understand the effect of lignans on cell cycle, we examined several cell cycle regulators, cyclins D1 and E and CDK4, which have been known to regulate the cell cycle of breast cancer cells under estrogen stimulation." (PMID 28152041, 2017). "In this review, we outline the preclinical and clinical advancement of these three orally bioavailable and highly selective CDK4/6 inhibitors in breast cancer." (PMID 28438180, 2017). "We have previously demonstrated the impact of CDK4 inhibition, in combination with doxorubicin chemotherapy, to reduce hormone receptor positive, cyclin D-overexpressing breast cancer cell growth." (PMID 29137393, 2017).
breast cancer (continued). "Next, to relate the CDK4 modification profiles to PD0332991 sensitivity in breast cancer cell lines, we selected 20 previously studied cell lines." (PMID 28566333, 2017). "Resistant cells were sensitised to the CDK4/CDK6 inhibitor palbociclib, which is currently approved for therapy of certain breast cancers and, like other CDK4/CDK6 inhibitors, is undergoing clinical trials for other types of cancer." (PMID 29222471, 2017). "MALAT1 was reported to be an endogenous regulator of breast cancer progression by down-regulating miR-124 and activating the CDK4/E2F1 signaling pathway." (PMID 28439401, 2017). "Currently, palbociclib is the only approved CDK4/6 inhibitor and is indicated for ER+ breast cancer in combination with letrozole or fulvestrant." (PMID 28418845, 2017). "As previously characterized, CDK4 was resolved by its charge into three main forms in breast cancer cell lines such as MCF7 cells and in breast tumor samples." (PMID 28566333, 2017). "In this study, we developed educational information tailored to different learning styles on the topic of treatment of metastatic estrogen receptor-positive (ER+) breast cancer using CDK4/6 inhibitors." (PMID 28743680, 2017). "This signature correctly predicts the CDK4 modification profile of tumors and breast cancer cell lines, and the sensitivity of the latter to PD0332991." (PMID 28566333, 2017). "CDK4/6 inhibition in combination with endocrine therapy is a promising new therapeutic strategy in hormone receptor-positive advanced breast cancer." (PMID 28978004, 2017). "Undoubtedly, HER2 and CDK4/6 are the two most important targets for breast cancer; biologicals targeted against the two targets not only increase objective response rates but also prolong PFS." (PMID 28454587, 2017). "Educational materials covered the topic of treatment of metastatic estrogen receptor-positive (ER+) breast cancer using cyclin-dependent kinases 4/6 (CDK4/6) inhibitors." (PMID 28743680, 2017). "This is evident by the breast cancer with PIK3CA mutations who appear to have had a partial response with a combination of PI3K inhibitor, CDK4/6 inhibitor and hormonal therapy." (PMID 28915716, 2017). "P16INK4A-enriched breast cancer models displayed unresponsive status to palbociclib treatment because CDK4/6 had already been largely suppressed by the endogenous p16INK4A." (PMID 28438180, 2017). "The essential roles of CDK4/6 in cell cycle regulation make them effective targets for cancer therapeutic intervention, especially in breast cancer." (PMID 28438180, 2017). "Here the authors show that treatment with CDK4/6 inhibitors activate autophagy in breast cancer cells; thus, combination of such inhibitors with autophagy inhibitors results in a synergistic effect on tumour growth." (PMID 28653662, 2017). "Subsequently, extensive studies were carried out to explore drugs inhibiting CDK4/6 and assess the efficacy and safety of these drugs in cancer, especially breast cancer." (PMID 28438180, 2017). "Serum TK1 activity is a promising pharmacodynamic marker of palbociclib in ER+ breast cancer, and its value in predicting response to CDK4/6 inhibitors warrants further investigation." (PMID 29162134, 2017). "ER-positive breast cancer cell line was the well-established population which was most sensitive to CDK4/6 inhibitors." (PMID 28438180, 2017). "The results of the research by Goel S indicated that the complex of cyclin D1 and CDK4 played important roles in the resistance of HER2-positive breast cancer cells to the anti-HER2 therapy." (PMID 28438180, 2017). "For example, in mouse models of breast cancers driven by the HER2/neu oncogene, loss of CDK4 activity is sufficient to inhibit the formation and proliferation of tumors." (PMID 29050219, 2017).
breast cancer (continued). "Inhibition of the p16INK4a/cyclin D/CDK4/6/RB pathway is an effective therapeutic strategy for the treatment of estrogen receptor positive (ER+) breast cancer." (PMID 28418845, 2017). "Third, although the 11‐gene signature was developed exclusively using the gene expression data of tumors, it predicted the observed CDK4 modification profiles in 24 of 25 breast cancer cell lines." (PMID 28566333, 2017). "Specifically, the profiling of a breast cancer cell line panel with palbociclib, a selective CDK4/6 inhibitor, demonstrated that CDK4/6 inhibitors are exquisitely effective at inhibiting the growth of ER+ cells." (PMID 28418845, 2017). "Our study provides the first evidence that serum TK1 activity as early as 2 weeks following CDK4/6 inhibitors is highly correlated with tumor cell proliferation response in patients with early-stage HR+ breast cancer." (PMID 29162134, 2017). "Mice models with ERBB2-overexpressing breast carcinoma showed that CDK4/6 was pivotal to the maintenance of the disease." (PMID 28438180, 2017). "Together, the data herein provide insight into the impact of CDK4/6 inhibition on ER+/HER2- models of breast cancer and the relevance to breast cancer clinical outcomes." (PMID 27564114, 2016). "Over-expression of CDK4 has been discovered in numerous of malignant neoplasms, including glioma, breast cancer, and lung cancer." (PMID 27166267, 2016). "CDK4 is overexpression in several cancer comprising of breast cancer, pancreas cancer, clear cell renal cell carcinoma, and colorectal cancer." (PMID 27818681, 2016). "The results showed that MALAT1 overexpression accelerated breast cancer cells proliferation, whereas CDK4-siRNA inhibited cancer cell proliferation." (PMID 26918449, 2016). "Over-expression of CDK4 has been discovered in numerous of malignant neoplasms, including breast cancer, glioma, and CRC." (PMID 27302926, 2016). "Basal-B cells express high CD44 and CDK4, along with high levels of the mesenchymal marker vimentin, while basal-A or luminal-like breast cancer cells display higher CD24 level with a high expression level of the epithelial marker E-cadherin." (PMID 27759034, 2016). "InuA upregulated the expression of p21 and Bax, induced the cleavage of PARP, and reduced the expression of Cdk2, Cdk4, Cdk6, Cyclin D1, Cyclin E, c-Myc, and Bcl2 in both breast cancer cell lines." (PMID 27105525, 2016). "We validated that the treatment with MALAT1-siRNA and CDK4 attenuated the effect of MALAT1 on breast cancer cells proliferation." (PMID 26918449, 2016). "It controls focal adhesion and androgen-related cell migration in human fibrosarcoma and Cyclin D1/cyclin-dependent kinase 4 mediated cell migration in breast cancer." (PMID 27124473, 2016). "The data showed that CDK4 was inhibited at both mRNA and protein levels in breast cancer cells treated with MALAT1-siRNA compared with MALAT1-sc." (PMID 26918449, 2016). "Recently, mTORC or CDK4/6 inhibition has been shown to sensitize PIK3CA mutant breast cancers to α-specific PI3K inhibitors." (PMID 27048245, 2016). "In searching for downstream targets of miR-124, we found that CDK4 was a direct target of miR-124 in breast cancer." (PMID 26918449, 2016). "Despite resistance to letrozole or taselisib, the cells were sensitive to taselisib in combination with other ER+ breast cancer therapies, docetaxel and the PD-0332991 CDK4/6 inhibitor." (PMID 27382432, 2016). "PD-0332991 (Palbociclib) is a CDK4/6 small molecule inhibitor currently under evaluation in the clinic for ER+ breast cancer in combination with letrozole." (PMID 27382432, 2016). "The results also showed that MALAT1-siRNA repressed breast cancer cell proliferation, whereas CDK4 overexpression induced breast cancer cell proliferation." (PMID 26918449, 2016). "In spite of the clinical data, the impact of CDK4/6 inhibition on breast cancer models and the significance related to patient subtypes and signaling pathways remains surprisingly scant." (PMID 27564114, 2016).
breast cancer (continued). "Here we review the mechanism of action, the rationale for the use in luminal breast cancer, and the available clinical data for CDK4/6 inhibitors." (PMID 27429659, 2016). "Several tumor types, including leukemia, breast cancer and lung cancers, are dependent on cyclin D-dependent kinase activity, and we have previously identified CDK4 as a target of miR-124." (PMID 26918449, 2016). "The selective CDK4/6 inhibitor palbociclib has shown promising results in metastatic luminal breast cancer when used in combination with endocrine therapy both in the first-line setting as in pretreated women." (PMID 27429659, 2016). "Together, these data indicate that there is a highly conserved gene expression program repressed by CDK4/6 inhibitors that transcends breast cancer subtypes." (PMID 27564114, 2016). "Evidence indicates that dysregulation of the cyclin D1:CDK4/6 axis has a role in breast cancer, with some tumors overexpressing cyclin D1." (PMID 26857361, 2016). "Further evidence for their role in malignant pathogenesis derives from studies demonstrating that the cyclin D1:CDK4/6 axis is critical for breast cancer maintenance and progression." (PMID 26857361, 2016). "In a series of preclinical studies using cell line models of human breast cancers, we demonstrated significant growth inhibitory activity of palbociclib (PD-0332991), which is a highly selective inhibitor of CDK4/6." (PMID 26857361, 2016). "The opportunity to target CDK4/6 in HER2-amplified breast cancer remains a very rational goal given the biology and preclinical data demonstrating synergy with trastuzumab." (PMID 26857361, 2016). "In previous study, we found that Cyclin-dependent kinase 4 (CDK4) is a direct target of miR-124 and that miR-124 inhibited cell proliferation via CDK4 in breast cancer." (PMID 26918449, 2016). "Because of the favorable toxicity profile and the significant prolongation of PFS, the combination of a CDK4/6 inhibitor with endocrine therapy will most probably be the first-line therapy of choice for most patients with advanced luminal breast cancer." (PMID 27429659, 2016). "Three different CDK4/6 inhibitors (palbociclib, abemaciclib and ribociclib) are in clinical development for the treatment of patients with HR+/HER2neg breast cancer, mostly in combination with endocrine therapy." (PMID 27634906, 2016). "Taken together, miR-124 is suppressed by MALAT1, and involved in cell proliferation and the cell cycle via the CDK4/E2F1 signaling pathway in breast cancer." (PMID 26918449, 2016). "Based on these data, clinical trials were initiated that demonstrated a significant impact of CDK4/6 inhibitors on the progression of metastatic ER+/HER2- breast cancer in combination with endocrine therapy." (PMID 27564114, 2016). "In our previous studies, we found that miR-124 inhibited cell proliferation by targeting CDK4 in breast cancer, however, the mechanism of miR-124 expression remains to be elucidated." (PMID 26918449, 2016). "The data suggested that MALAT1 was involved in cell proliferation through the CDK4/E2F1 signaling pathway in breast cancer." (PMID 26918449, 2016). "Numerous lines of evidence point to an important role of a dysregulated cyclin D1:CDK4/6 complex in both the initiation and progression of many cancers, including breast cancer." (PMID 26857361, 2016). "Inhibitors against CDK4/6, which induce G1 to S phase cell cycle arrest, have demonstrated therapeutic efficacy in both endocrine therapy naïve and resistant ER+ breast cancer." (PMID 27486754, 2016). "We found that combined inhibition of the Rb transcriptional repressor and the FZR1 APC/C co-activator eliminates the normal requirement for CDK4/6-cyclin D kinase activity in C. elegans and human breast cancer cells." (PMID 25562820, 2015). "The amplification of CDK4, located on chromosome 12q13-14, has been reported in sarcomas, glioblastomas and breast cancers." (PMID 26528855, 2015).